MR1 (major histocompatibility complex, class I-related)
Diseases named in the same sentence as MR1 in open-access papers (continued):
Sharing a sentence is not in itself a finding about the gene and the disease.
Sepsis (2 papers, 2015 to 2020). Sepsis is defined as life-threatening organ dysfunction caused by a dysregulated host response to infection. "In the CLP model of polymicrobial sepsis, we saw that MR1-deficient mice (Mr1-/-) which lack MAIT cells, had significantly increased sepsis-related mortality compared to WT mice." (PMID 33164745, 2020). "The microbiota associated with Mr1-/- mice may differ from WT mice; therefore, we examined whether such differences affect susceptibility to sepsis." (PMID 33164745, 2020). "Thus, we next sought to determine the cause of reduced tissue cytokine production of Mr1-/- mice during sepsis." (PMID 33164745, 2020). "Our experimental data from the ExPEC model of sepsis, as well as from experiments where bedding was transferred between Mr1-/- and WT mice, suggest that the differences in mortality observed with CLP are unlikely to be due to differences in the microbiota." (PMID 33164745, 2020). "The majority (11/15,~73%) of Mr1-/- mice died 24 to 48 hr following induction of sepsis, while the majority (13/15,~87%) of WT mice survived up to 100 hr after sepsis." (PMID 33164745, 2020). "As we observed in the CLP, polymicrobial model of sepsis, Mr1-/- mice had significantly higher mortality from ExPEC sepsis, compared to WT mice." (PMID 33164745, 2020). "(C) The bedding transfer procedure (detailed in Materials and methods section) was used to exchange gut microbiome between age-matched Mr1-/- and WT mice (total n = 31 for Mr1-/- mice and total n = 30 for WT mice) before inducing sepsis by CLP." (PMID 33164745, 2020). "In both a polymicrobial model of sepsis (i.e. CLP) and a monomicrobial model using a clinical isolate of ExPEC, we found that MAIT-deficient (Mr1-/-) mice have higher mortality and that this is associated with a higher bacterial burden." (PMID 33164745, 2020). "Evolutionary conservation of CD1d and MR1 recognition across mammalian species makes animal models of sepsis particularly useful for studying NKT and MAIT cells." (PMID 26322041, 2015). "Recent studies have implicated unconventional, innate-like T lymphocytes, including CD1d- and MR1-restricted T cells as effectors and/or regulators of inflammatory responses during sepsis." (PMID 26322041, 2015). "Mr1-/- mice had higher sepsis-induced mortality and bacterial burden compared to wild type mice." (PMID 33164745, 2020). "We examined the immune responses in C57BL/6 wild type (WT) or MR1 knock-out (Mr1-/-; i.e. MAIT depleted) mice using the cecal ligation and puncture (CLP) model of polymicrobial sepsis." (PMID 33164745, 2020). "We also found that Mr1-/- mice had lower levels of tissue cytokines (IFN-γ, TNF-α, IL-17, GM-CSF) than that in WT mice following induction of sepsis." (PMID 33164745, 2020). "(A) Age-matched Mr1-/- and WT mice (n = 15 per group) underwent CLP to induce polymicrobial sepsis." (PMID 33164745, 2020).
type 1 diabetes (2 papers, 2020 to 2025). "For instance, in type 1 diabetes and graft-versus-host disease models, Mr1−/− mice demonstrated worsened disease outcomes due to impaired barrier functions 64,65." (PMID 39918959, 2025).
Action tremor (1 paper, 2013). A tremor present when the limbs are active, either when outstretched in a certain position or throughout a voluntary movement. "PNKD due to MR-1 mutation may exist even in the presence of action tremor." (PMID 24171125, 2013).
allergic contact dermatitis (1 paper, 2023). An inflammatory skin condition caused by an immune response to direct contact between the skin and an allergen. "In this study, we investigated the function of MR1 in allergic contact dermatitis (ACD) by examining wild-type (WT) and MR1-deficient (MR1-/-) mice in which ACD was induced with 2,4-dinitrofluorobenzene (DNFB)." (PMID 37409131, 2023).
alopecia (1 paper, 2024). Hair loss usually from the scalp. "Goat wild-type genes defective for MR1 can be used as an animal model to study alopecia." (PMID 38628581, 2024).
bacterial pneumonia (1 paper, 2024). Acute infection of the lung parenchyma caused by bacteria (e.g., Streptococcus pneumoniae, Haemophilus influenzae, Chlamydia pneumoniae, Mycoplasma pneumoniae, and Legionella pneumophila). "Another example of MAIT cell driven protection during bacterial pneumonia includes the aerosol-mediated infection with Mycobacterium bovis BCG in which MR1-KO mice showed higher lung bacterial burden than WT counterparts at early time-points after infection." (PMID 39128630, 2024). "Several riboflavin-producing bacteria have been shown to activate MAIT cells in an MR1-dependent manner, ultimately leading to protective roles for MAIT cells in bacterial pneumonia." (PMID 39128630, 2024). "Subsequently, several models of murine bacterial pneumonia highlight key and non-redundant protective roles for MAIT cells underpinned by diverse (MR1-dependent and independent) mechanisms of activation as summarised below." (PMID 39128630, 2024).
benign ovarian tumors (1 paper, 2011). "Tissue MR-1 mRNA levels were analyzed by RT-PCR and quantitative real-time PCR to investigate the expression of MR-1 in malignant and benign ovarian tumors." (PMID 21702971, 2011).
cardiac hypertrophy (1 paper, 2015). "While overexpression of MR-1 in mice enhances cardiac hypertrophy stimulated by angiotensin II, overexpression of MR-1 in NRVM induces sarcomeric organization and translocation of myomesin from the nucleus to the cytoplasm, similar to SUMO overexpression." (PMID 25961035, 2015).
chronic obstructive pulmonary disease (1 paper, 2025). A chronic and progressive lung disorder characterized by the loss of elasticity of the bronchial tree and the air sacs, destruction of the air sacs wall, thickening of the bronchial wall, and mucous accumulation in the bronchial tree. "MR1-deficient mice were partially protected from the development of chronic obstructive pulmonary disease (COPD) features that were associated with CS exposure." (PMID 39820322, 2025).
coeliac disease (1 paper, 2020). "Although low levels of MR1-specific T cells were detected in most individuals, MR1-tetramer-positive cells were enriched in some individual samples, including in newly diagnosed coeliac disease and Merkel cell carcinoma." (PMID 32299647, 2020).
cognitive decline (1 paper, 2023). "There was an age-dependent cognitive decline in young adult MR1-/- mice which could be rescued by the adoptive transfer of MAIT cells, but not conventional CD4+ or CD8+ T cells, into MR1-/- mice." (PMID 37536148, 2023).
coronary disease (1 paper, 2017). "Recently, a novel susceptibility locus in MR1 has been associated with coronary disease, likely as a result of dysregulated endothelial function and atherogenesis." (PMID 28178938, 2017).
depression (1 paper, 2016). "NR3C2 codes for mineralocorticoid receptor 1 (MR1) and antidepressants were shown to modulate MR hormone-binding and expression in the context of the corticosteroid receptor hypothesis of depression." (PMID 27091189, 2016).
dermatitis (1 paper, 2023). An inflammatory process affecting the skin. "In the absence of exogenous stimulation, MR1-/- mice exhibited a similar pinna thickness compared to WT mice, suggesting that MR1-/- mice do not develop spontaneous dermatitis." (PMID 37409131, 2023).
emphysema (1 paper, 2025). "Indeed, our data using Mr1−/− mice show that the development of lung inflammation and altered function and emphysema were all reduced, showing that MR1 and MAIT cells are involved in the induction of the hallmark features of COPD." (PMID 39820322, 2025). "We observed the development of enlarged alveoli and emphysema in the WT CS group; however, importantly, Mr1−/− CS groups did not develop emphysema." (PMID 39820322, 2025).
glomerulonephritis (1 paper, 2019). A renal disorder characterized by damage in the glomeruli. "Histopathological analysis of kidneys revealed decreased severity of glomerulonephritis by MR1 deficiency, as shown by the decreased glomerulonephritis scores in MR1−Fc− mice compared with MR1+Fc− mice." (PMID 31849932, 2019).
HCMV infection (1 paper, 2023). "Here we demonstrate that HCMV infection efficiently suppresses MR1 surface expression and reduces total MR1 protein levels." (PMID 36845106, 2023). "This concept was of particular interest when examining regulation of MR1 during HCMV infection because the closely related molecule MHC I is downregulated on HCMV antigen positive cells but upregulated on bystander cells that do not stain for HCMV antigens." (PMID 36845106, 2023). "Together, these results confirm impairment of bacterial-driven, MR1-dependent MAIT cell activation by HCMV infection." (PMID 36845106, 2023). "HCMV infection was capable of efficiently suppressing MR1 surface expression driven by either synthetic MR1 ligand or provided by treatment with bacteria having an intact vitamin B2 biosynthesis pathway." (PMID 36845106, 2023). "Functional assays with primary MAIT cells demonstrated the ability of HCMV infection to inhibit bacterially driven, MR1-dependent activation using both neutralizing antibodies and engineered MR1 knockout cells." (PMID 36845106, 2023). "Through in vitro human cytomegalovirus (HCMV) infection in the presence of MR1 ligand we investigate the modulation of MR1 expression." (PMID 36845106, 2023). "Together, these results demonstrate impairment of bacterial-driven, MR1-dependent MAIT cell activation by HCMV infection." (PMID 36845106, 2023). "To test the ability of gpUS9 to regulate MR1 in the context of HCMV infection we assayed a US9 deletion mutant, based on the Merlin strain." (PMID 36845106, 2023). "Here we report modulation of surface and total MR1 protein by HCMV infection, and implicate the HCMV US9 gene product as contributing to this phenotype." (PMID 36845106, 2023). "The functional consequences of MR1 modulation by HCMV infection are explored in coculture activation assays with either Jurkat cells engineered to express the MAIT cell TCR or primary MAIT cells." (PMID 36845106, 2023). "When % CD69+ was used to assess MAIT cell activation all significance was lost, suggesting that in this assay set up both HCMV infection and the MR1 neutralizing antibody were affecting the degree of activation more significantly than the proportion of activated MAIT cells." (PMID 36845106, 2023). "To determine any impact on cell surface and total MR1 during HCMV infection, we utilized a BAC derived virus based on the low passage Merlin HCMV strain engineered to express GFP driven by an internal ribosome entry site (IRES) downstream of the HCMV IE2 (Merlin-GFP)." (PMID 36845106, 2023). "Thus, HCMV infection suppresses MR1-dependent activation of primary MAIT cells." (PMID 36845106, 2023). "gpUS9 expression in isolation lead to a specific reduction in total MR1, using both untagged and GFP tagged MR1 mirroring the reduction in MR1 levels demonstrated following HCMV infection." (PMID 36845106, 2023).
HIV-1 infection (1 paper, 2020). The type species of lentivirus and the etiologic agent of acquired immunodeficiency syndrome (AIDS). "In contrast, expression of CD161 in the MR1 tetramer-defined MAIT cell population was unchanged and consistently high throughout the period following HIV-1 infection." (PMID 31937782, 2020).
Hyperglycemia (1 paper, 2020). An increased concentration of glucose in the blood. "Treatment with anti‐CD45RB or anti‐MR-1 alone failed to control hyperglycemia in any xenograft recipient (n = 5)." (PMID 33270650, 2020). "We reimplanted xenogeneic islets into mice in which the reversal of hyperglycemia had failed and explored whether euglycemia could be maintained over the long term following dual anti-CD45RB plus anti-MR-1 antibody treatment." (PMID 33270650, 2020). "Not surprisingly, treatment with anti‐CD45RB or anti‐MR-1 alone failed to control hyperglycemia in any recipient (n = 5)." (PMID 33270650, 2020).
ischemia (1 paper, 2023). A hypoperfusion of the BLOOD through an organ or tissue caused by a PATHOLOGIC CONSTRICTION or obstruction of its BLOOD VESSELS, or an absence of BLOOD CIRCULATION. "Similarly, a lack of MR1 reduces the overall severity of ischemia in mice." (PMID 36944969, 2023).
leishmaniasis (1 paper, 2022). Infectious disease that is transmitted through the bite of hematophagous female phlebotomine sand flies. "This study showed that in response to L. infantum, human peripheral blood MAIT cells from children with leishmaniasis produced TNF and IFN-γ in an MR1-dependent manner." (PMID 36189274, 2022).
lymphopenia (1 paper, 2010). Reduction in the number of lymphocytes. "To determine whether the blocking effect of MR1 on HNT CD4+ T cell proliferation was driven by lymphopenia and/or the HA antigen, we performed adoptive transfer experiments in lymphopenic MR1 treated BALB/c mice." (PMID 20856822, 2010).
malignant glioma (1 paper, 2012). A grade III or grade IV glioma arising from the central nervous system. "The distribution of MR1-1-PE38KDEL at a concentration of 25 ng/mL by CED was monitored by coinfusion with the low molecular weight tracer gadolinium-diethylene triamine pentaacetic acid (Gd-DTPA) and 124I-labeled human serum albumin in a malignant glioma patient." (PMID 22400035, 2012).
metastatic cancer (1 paper, 2024). A carcinoma which has spread from the original site of growth to another anatomic site. "Subsequently, the IHC tests were performed to detect the expression of MR‐1 in 40 NSCLC patients and their tissue arrays of corresponding metastatic cancer through TMA (LUM961), and found that MR‐1 was highly expressed in metastatic cancer tissues." (PMID 38342606, 2024).
Mycobacterium avium infection (1 paper, 2025). "We also tested the effect of N19 on Mycobacterium avium infection, which is a nontuberculous mycobacteria (NTM), and found that N19 decrease MR1-dependent antigen presentation." (PMID 40758737, 2025).
myelofibrosis (1 paper, 2022). A partial or complete replacement of the bone marrow stroma by fibrous tissue. "Both class I and II HLA genes are down‐regulated in PV, ET and myelofibrosis, with progressive downregulation of certain genes [BAT2L, HLA Complex Group 11 (HCG11) and major histocompatibility complex (MHC), Class I‐related (MR1)] in ET versus PV versus myelofibrosis." (PMID 34618358, 2022).
nonalcoholic steatohepatitis (1 paper, 2021). "Methionine and choline-deficient diet (MCD), which is commonly applied to induce nonalcoholic steatohepatitis (NASH) resulted in a more severe hepatic steatosis in MR1 knockout mice compared to wild type." (PMID 33535703, 2021).
oral diseases (1 paper, 2023). "In addition, mucosa-associated invariant T cells are reportedly involved in the pathogenesis of oral diseases and can be activated by RF in an MR1-dependent manner." (PMID 36625571, 2023).
ovarian carcinoma (1 paper, 2011). A malignant neoplasm originating from the surface ovarian epithelium. "Further studies are needed to clarify whether MR-1 is an early diagnostic marker for ovarian cancer and a possible therapeutic target." (PMID 21702971, 2011). "Further studies are needed to clarify whether MR-1 is an early diagnostic marker for ovarian cancer and to develop its full therapeutic potential." (PMID 21702971, 2011). "Quantitative real-time PCR also showed that MR-1 expression was significantly higher in tumor tissues from ovarian cancer patients (n = 26) than in control patients (n = 25) (P < 0.05)." (PMID 21702971, 2011). "Immunohistochemical staining of 26 ovarian cancer tissue samples and 20 ovarian cyst samples showed that the MR-1 protein was located in both the cytoplasm and nuclei of ovarian carcinoma cells, whereas the epithelial cells of the cysts were negative." (PMID 21702971, 2011). "Reverse-transcription polymerase chain reaction (PCR) and quantitative real-time PCR were used to detect MR-1 mRNA levels in tissue samples from 26 ovarian cancer patients and 25 controls with benign ovarian disease." (PMID 21702971, 2011). "This further suggests that MR-1 plays an important role in ovarian cancer cell adhesion, spreading and invasion." (PMID 21702971, 2011). "293T cells overexpressed MR-1, and cellular spread and invasion were enhanced after transfection of the pMX-MR-1 plasmid, suggesting that MR-1 is critical for ovarian cancer cell growth." (PMID 21702971, 2011). "Diffuse staining for MR-1 was observed in ovarian cancer cells, particularly serous papillary ovarian cancer cells, compared with the benign control group." (PMID 21702971, 2011). "This is the first study showing that expression of MR-1 is increased in ovarian cancer tissues at both the mRNA and protein levels compared with benign control tissues." (PMID 21702971, 2011). "MR-1 was overexpressed in ovarian cancer tissues and SKOV3 cells." (PMID 21702971, 2011). "Taking all the evidence into account, we hypothesized that MR-1 may play a role in the development and progression of ovarian cancer, probably by promoting cell proliferation and invasion." (PMID 21702971, 2011). "This study shows that MR-1 is overexpressed in ovarian cancer tissue and cell lines." (PMID 21702971, 2011). "The present study examined MR-1 expression in ovarian cancer tissues and a cancer cell line." (PMID 21702971, 2011). "Taken together, these results provide the first evidence of the cellular and molecular mechanisms by which MR-1 might serve as a novel biological marker and potential therapeutic target for ovarian cancer." (PMID 21702971, 2011). "Western blotting showed a higher level of MR-1 protein expression in ovarian cancer tissues." (PMID 21702971, 2011). "The aim of this study was to examine whether MR-1 is a predictor of ovarian cancer and its value as a therapeutic target in ovarian cancer patients." (PMID 21702971, 2011). "Thus, MR-1 is potentially a novel therapeutic target for the treatment of ovarian cancer." (PMID 21702971, 2011). "Finally, the response of MR-1 to treatment with anti-cancer drugs was assessed to identify whether it functions as a novel biological marker and therapeutic target for ovarian cancer." (PMID 21702971, 2011). "Thus, MR-1 may be a novel biological marker and potential therapeutic target for the treatment of ovarian cancer." (PMID 21702971, 2011). "There are no reports examining the role of MR-1 in ovarian cancer." (PMID 21702971, 2011). "However, the significance of MR-1 in human ovarian cancer has not yet been explored." (PMID 21702971, 2011).
overactive bladder (1 paper, 2014). Symptom of overactive detrusor muscle of the urinary bladder that contracts with abnormally high frequency and urgency. "IL22 could serve as a regulatory cytokine that contributes to the physiopathology of overactive bladder by modulating the acetylcholine response through inhibition MR1 expression." (PMID 25354343, 2014).
pancreatitis (1 paper, 2022). Inflammation of the pancreas. "Pancreatitis was ameliorated in the resulting Bcl11bΔiThy × Mr1–/– mice and they survived longer." (PMID 36376329, 2022).
parasite infection (1 paper, 2022). "Cells responsive to parasite infection appeared to make up a fraction of MR1-5-OP-RU-restricted MAIT cells." (PMID 36189274, 2022).
pneumococcal infection (1 paper, 2014). Infections with bacteria of the species streptococcus pneumoniae. "Now that MAIT Ags have been identified, the use of MR1-Ag tetramers will enable the characterization and tracking of MAIT cells during pneumococcal infections in animal models and in humans." (PMID 25299581, 2014).